PIK3R1 (phosphoinositide-3-kinase regulatory subunit 1)
Diseases named in the same sentence as PIK3R1 in open-access papers (continued):
Sharing a sentence is not in itself a finding about the gene and the disease.
ovarian carcinoma (continued). "PIK3R1 loss renders ovarian cancer cells vulnerable to inhibition of AKT or JAK2/STAT3." (PMID 30755611, 2019). "Our findings showed that blockade of AKT or STAT3 may benefit ovarian cancer patients harboring PIK3R1 copy number loss or reduced PIK3R1 expression." (PMID 30755611, 2019). "Copy number loss of PIK3R1 (p85α) most commonly occurs in ovarian cancer among all cancer types." (PMID 30755611, 2019). "The prevalence of PI3K pathway mutations, including PIK3R1, PIK3CA, and PTEN was 13.5% (19/141) in ovarian cancers." (PMID 39858051, 2025). "PIK3R1 mRNA expression was significantly decreased in ovarian cancers compared with control tissues (p = 0.003, Mann–Whitney U test)." (PMID 39858051, 2025). "Among various cancers, copy-number deletion of PIK3R1 is most commonly observed in ovarian cancer, where its deletion activates AKT and induces p110-independent JAK2/STAT3 signaling through phosphorylation changes in the docking protein Gab2." (PMID 40657399, 2025). "This discrepancy in these study results indicate that the prognostic significance of PIK3R1 expression warrants further investigations in ovarian cancer patients." (PMID 39858051, 2025). "PIK3R1 mRNA was downregulated in 95.8% (138/144) of ovarian cancers relative to the control group’s mean, indicating the relevance of PIK3R1 in ovarian tumorigenesis." (PMID 39858051, 2025). "We aimed to evaluate PIK3R1 alterations in ovarian cancers in the context of their clinicopathological characteristics, other molecular changes, and patient prognoses." (PMID 39858051, 2025). "In ovarian cancer, circPLPP4 targets miR-136, acting as a competitive endogenous RNA to regulate PIK3R1 expression and enhance cisplatin resistance." (PMID 40657399, 2025). "The “circPLAPP4- miR-136- PIK3R1” axis as a regulatory whole co-regulates CDDP resistance in ovarian cancer." (PMID 38184597, 2024). "Surprisingly, the PIK3R1 expression level in ovarian cancer tissues was markedly decreased compared to begin ovarian tissues." (PMID 37781028, 2023). "Mechanistically, low expression of YTHDC1 promotes ovarian cancer tumorigenesis via PIK3R1/STAT3/GANAB axis." (PMID 37781028, 2023). "In the current study, we confirmed that PIK3R1 is significantly lowly expressed in ovarian cancer, thereby ameliorating the tumor-promoting property of YTHDC1 deficiency." (PMID 37781028, 2023). "The role of PIK3R1 in ovarian cancer was further explored by overexpressing PIK3R1 in YTHDC1 deficient SKOV3 and A2780 cells." (PMID 37781028, 2023). "At the mechanistic level, we showed that LRRC4 binds to the c-SH2 domain of PIK3R1 to inhibit the activity of PIK3R1 and subsequently disrupts E-cadherin-dependent collective invasion of ovarian cancer cells mediated by the PIK3R1 signaling pathway." (PMID 32117780, 2020). "Having established that PIK3R1 loss activates STAT3 and AKT pathways in ovarian cancer cells, we reasoned that cells with PIK3R1 loss would be sensitive to inhibitors of these two pathways." (PMID 30755611, 2019). "Responses to the inhibitors in vivo were evaluated in ovarian cancer xenografts injected i.p. with PIK3R1-shRNA stably expressing SKOV3 cells." (PMID 30755611, 2019). "Our findings herein demonstrated that reduced PIK3R1 expression favors ovarian cancer tumorigenesis through AKT and AKT-independent activation of STAT3 signaling." (PMID 30755611, 2019). "Our data indicate the role of PIK3R1 in ovarian cancer development and define a significant group of patients with different PIK3R1 alterations that may potentially benefit from treatment with PI3K inhibitors." (PMID 39858051, 2025). "Collectively, these data suggest that PIK3R1 copy number losses are frequent in ovarian cancers and other cancer types and may have tumorigenic potential." (PMID 39858051, 2025). "The blockade of AKT or STAT3 may benefit ovarian cancer patients experiencing copy number losses or reduced expression of PIK3R1." (PMID 40657399, 2025).
ovarian carcinoma (continued). "We assessed PIK3R1 expression levels in ovarian cancer subtypes." (PMID 39858051, 2025). "Consequently, in mice, reduced PIK3R1 expression promoted oncogenic transformation and metastatic dissemination of ovarian cancer." (PMID 39858051, 2025). "Our study revealed that PIK3R1 is lowly expressed in ovarian cancers." (PMID 39858051, 2025). "This study may be important since we found that there is a significant group of ovarian cancer patients with different PIK3R1 alterations that may potentially benefit from treatment with PI3K and AKT inhibitors." (PMID 39858051, 2025). "Our data provide insight into the clinicopathological and molecular characteristics of tumors with PIK3R1 dysfunction and may have important implications in the future planning of ovarian cancer therapy with PI3K pathway inhibitors." (PMID 39858051, 2025). "The current study showed that the vast majority of ovarian cancers carry PIK3R1 alterations (>90%)." (PMID 39858051, 2025). "Similarly, low PIK3R1 mRNA expression was found in ovarian cancer and many other human cancers in the OncoMine microarray database." (PMID 39858051, 2025). "It has been reported that the loss of PIK3R1 could activate AKT and STAT3 signaling in ovarian cancer." (PMID 37781028, 2023). "Thus, our data suggest that PIK3R1 as a crucial downstream target of YTHDC1 for inhibiting the progression of ovarian cancer." (PMID 37781028, 2023). "Collectively, these results indicate that PIK3R1 is a direct target of YTHDC1 in ovarian cancer." (PMID 37781028, 2023). "The PIK3R1 protein level in the ovarian cancer tissues were further assessed by IHC staining." (PMID 37781028, 2023). "PIK3R1 is currently considered as an oncogene in ovarian cancer." (PMID 32117780, 2020). "Therefore, although prediction algorithms allowed us to classify the W624R amino acid change in PIK3R1 as possibly deleterious and damaging the protein product, it was difficult to predict its actual impact on ovarian cancer." (PMID 32075097, 2020). "Finally, we evaluated the clinical importance of PIK3R1 alterations in ovarian cancer patients." (PMID 39858051, 2025). "However, the significance of PIK3R1 encoding the PI3K regulatory subunit, an inhibitor of the PI3K catalytic subunit encoded by PIK3CA, in ovarian cancer development is largely unknown." (PMID 39858051, 2025). "Moreover, PIK3R1 also works as an oncogene in ovarian cancer and colonic cancer." (PMID 34765599, 2021). "Here, we characterize a novel mechanism, in which a PIK3R1 fusion paradoxically activates the ERK1/2 pathway, increases ovarian cancer cell migration and chemoresistance, and thereby potentially facilitates metastatic dissemination." (PMID 38489912, 2024). "For example, increased PIK3R1 expression has been identified to impair anti‐tumor effect through PI3K‐Akt activation in breast and ovarian cancer chemotherapy." (PMID 36911092, 2023). "Furthermore, GEPIA database analysis showed that only four genes, PIK3R1, JUNB, RHOBTB2, and SLC25A37, were expressed at low level in ovarian cancer and were correlated positively with YTHDC1." (PMID 37781028, 2023). "Concordantly, STAT5 is not activated in PIK3R1-depleted ovarian cancer cells." (PMID 30755611, 2019). "Moreover, a lower expression level of PIK3R1 induced by YTHDC1 knockdown leads to activation of STAT3 signaling, which further promotes GANAB expression in the nucleus, followed by an increase of GANAB-mediated N-glycan biosynthesis in ovarian cancer cells, which promotes ovarian cancer progression." (PMID 37781028, 2023).
colon carcinoma (18 papers, 2012 to 2025). "PIK3R1 mutation has been found to occur infrequently in numerous cancer types, including ovarian and colon cancer, and the present study showed a low frequency of alteration of PIK3R1 in HCC." (PMID 25120700, 2014). "PIK3R1 mutations were identified in 43% of endometrial cancer, 4% of ovarian cancer and 2% of colon cancer." (PMID 25120700, 2014). "Interestingly, ∼45% of PIK3R1-mutant colon cancer specimens and ∼22% of PIK3R1-mutant endometrioid endometrial cancers also carried mutations of PIK3CA." (PMID 23166678, 2012). "Finally, loss of PIK3R1 was preferentially observed in descending colon tumors." (PMID 29755661, 2018). "Expression levels of Pcna, Ccnd1(CyclinD1), Bcl2, Itga2, Itgb1, Fak, Pik3r1, Akt1, Mtor and Myc were remarkably upregulated and Bax was downregulated in colonic tumors of mice treated with S. moorei." (PMID 39990665, 2025). "Few data has been published on the SNP rs3730089 in the PIK3R1 gene, studied only in prostate and colon cancer." (PMID 29100280, 2017). "Normal cells express higher levels of PIK3R1 (which encodes p85α) than of PIK3R2 (p85β); in contrast, metastatic melanoma, invasive breast cancer and advanced colon carcinoma show a marked increase in PIK3R2 expression, which correlates with tumor grade." (PMID 27835880, 2016). "In addition to known oncogenic mutations in PIK3CA, recent cancer genome sequencing efforts have identified recurrent somatic mutations of PIK3R1 in GBM, endometrial, and colon cancers." (PMID 23166678, 2012).
Obesity (16 papers, 2008 to 2025). Accumulation of substantial excess body fat. "PIK3 has both catalytic (PIK3CA and PIK3CD) and regulatory subunits (PIK3R1), being the last one critical for obesity studies since its expression is linked to insulin metabolism and initiation of inflammation processes." (PMID 32599690, 2020). "Therefore, we conjecture that PIK3R1 may play a critical role in obesity and lipidosis associated with low testosterone." (PMID 34827785, 2021). "This prediction highlights the pivotal role of PIK3R1 in regulating adipogenesis, suggesting a promising avenue for obesity treatment." (PMID 41032481, 2025). "By integrating network pharmacology and bioinformatics analysis, we identified PIK3R1 as the ultimate target for Crataegus pinnatifida combined with the obesity-related gut microbiota in the treatment of obesity." (PMID 41032481, 2025). "Strong binders to PIK3R1 were predicted to be quercetin, kaempferol and naringenin chalcone, suggesting their potential as therapeutic agents to treat obesity." (PMID 41032481, 2025). "Complementary bioinformatics analysis revealed four key targets associated with obesity onset: HSD11B1, RXRG, G6PD and PIK3R1." (PMID 41032481, 2025). "Through the bioinformatics analysis, we identified HSD11B1, RXRG, G6PD, and PIK3R1 as core genes for the interplay between Crataegus pinnatifida and the obesity-related gut microbiota in obesity regulation." (PMID 41032481, 2025). "The synergistic combination of Crataegus pinnatifida and the obesity-related gut microbiota holds promise as a novel therapeutic strategy for obesity by targeting PIK3R1 and modulating the PI3K/Akt signaling pathway." (PMID 41032481, 2025). "The present study aimed to evaluate how the gene expression and DNA methylation of PIK3R1, an obesity and insulin-related gene, change after RYGB." (PMID 32599690, 2020). "PIK3R1 mRNA expression was lower in gonadal adipose tissue of male offspring exposed to maternal obesity during lactation across the lifespan." (PMID 31300679, 2019). "Analysis combining both age groups, demonstrated that offspring exposed to maternal obesity during lactation had 12% lower PIK3R1 mRNA expression than offspring exposed to a control diet (P = 0.049)." (PMID 31300679, 2019). "By combining the targets identified via both approaches, PIK3R1 was selected as the likely protein target by which Crataegus pinnatifida and obesity-related gut microbiota may be able to treat obesity." (PMID 41032481, 2025). "In the present study, network pharmacology results showed that Crataegus pinnatifida combined with the obesity-related gut microbiota may treat obesity by targeting PIK3R1, PIK3CB, SRC, PIK3CA, PIK3 CD." (PMID 41032481, 2025). "Through network pharmacology analysis, we revealed that SMs of Crataegus pinnatifida and obesity-related gut microbiota could target obesity by interacting with PIK3R1, PIK3CB, SRC, PIK3CA and PIK3 CD." (PMID 41032481, 2025). "The LASSO regression models were built from data from obese and normal tissues, and the λ analysis indicated that the model achieved optimal predictive accuracy for obesity at λ = 4, leading to the identification of 4 core diagnostic genes, including HSD11B1, RXRG, G6PD and PIK3R1." (PMID 41032481, 2025). "Interestingly, heterozygous Pik3r1+/− mice are also protected from obesity; however, in contrast to Pik3r1+/R649W mice, they remain insulin sensitive." (PMID 37628845, 2023). "In an effort to establish the mechanisms whereby miR-100-3p controls adipogenesis as a means of highlighting novel therapeutic approaches to treating obesity, we utilized predictive bioinformatics algorithms to identify PIK3R1 a putative miR-100-3p target gene." (PMID 33221758, 2020). "The intersection of the results from these two plugins revealed that PIK3R1, PIK3CB, SRC, PIK3CA and PIK3 CD are core targets for the combined treatment of obesity via Crataegus pinnatifida andgut microbiota." (PMID 41032481, 2025).
Obesity (continued). "Our integrative approach using network pharmacology and bioinformatics predicts that targeting the PIK3R1 gene and modulating the PI3K/Akt signaling pathway can ameliorate obesity." (PMID 41032481, 2025). "When Pik3r1+/R649W mice were crossed with ob/ob mice, Pik3r1+/R649W-ob/ob mice do not develop obesity and hepatic steatosis." (PMID 37628845, 2023). "The biological processes “Platelet degranulation,” “Positive regulation of glucose import” and “Cellular response to insulin stimulus,” already found modulated in obesity (PDGFB, SERPING1 ADIPOQ, PIK3R1, IGF1) were further enriched in ObCRC with respect to Ob individuals." (PMID 30838002, 2019). "The NF-κB target genes JUN, PIK3R1, FOS, and IGF1R are enriched in the insulin signaling pathway which could contribute to obesity related disorders." (PMID 31013288, 2019). "Whole-body heterozygous deletion of the Pik3r1 regulatory subunits (Pik3r1+/−), but not knockout of Pik3r2, preserves whole-body WAT and skeletal muscle insulin sensitivity, despite severe obesity." (PMID 37628845, 2023).
liver cancer (15 papers, 2011 to 2025). An epithelial or non-epithelial malignant neoplasm that arises from the liver. "Notably, our analysis identified one UPR-associated protein, phosphoinositide-3-kinase regulatory subunit 1 (PIK3r1), as a favorable prognostic marker in liver cancer." (PMID 34356495, 2021). "Network pharmacology screened 185 intersection targets of cinnamic acid and liver cancer, of which 39 core targets (such as PIK3R1, AKT1, MAPK1) were identified as key regulatory hubs through protein interaction network and topological analysis." (PMID 40872596, 2025). "Comparing these findings with those provided by enrichment analysis four genes in particular, EGFR, MAPK3, MTOR, and PIK3R1, were identified as the main anti-liver cancer targets of F. indica and were chosen for molecular docking experiments." (PMID 35745580, 2022). "Liver cancer tissues displayed a higher expression of PIK3R1 in comparison to normal liver tissues." (PMID 39204124, 2024). "Besides, PIK3R3 displayed a more pronounced variation in liver cancer compared to normal tissues, in contrast to PIK3R1 and PIK3R2.In fresh clinical samples, we confirmed that PIK3R3 was overwhelmingly upregulated in HCC compared with paired normal tissues." (PMID 37212524, 2023). "Furthermore, our studies revealed that the EGFR, MAPK3, MTOR, and PIK3R1 genes are effective and potential therapeutic agents for lowering the incidence of liver cancer and potentially exhibiting therapeutic effects on liver cancer." (PMID 35745580, 2022). "It has been reported that PIK3A and PIK3R1, the genes that respectively encode the PI3K p110α and PI3K p85 subunits, are somatically mutated in many cancers, including liver cancer, and that these mutations promote the activation of the PI3K-AKT pathway and oncogenesis." (PMID 24223153, 2013). "The results of molecular docking predicted that several key targets of liver cancer (along with MTOR, EGFR, MAPK3, and PIK3R1) bind stably with the corresponding active ingredient of F. indica." (PMID 35745580, 2022). "INH-mediated histone Kinic upregulates PIK3R1 gene expression and activates the PI3K/Akt/mTOR signalling pathway in liver cancer cells, linking INH to tumourigenicity in the liver." (PMID 34545082, 2021). "Through topological analysis (betweenness ≥ 257.821, closeness ≥ 0.00237, degree ≥ 17.195), 39 core targets were screened, including PIK3R1, AKT1, MAPK1, etc., which may play a central role in the treatment of liver cancer." (PMID 40872596, 2025). "Fucoidan exerts its anti-liver cancer effect primarily by downregulating mRNA expression levels of target genes including AKT1, PI3K, PIK3R1, PIK3CA and other targets, inhibition of PI3K/Akt signaling pathway activation, and suppressing HepG2 cell proliferation." (PMID 40740310, 2025). "In liver cancer, circRHBDD1 can recruit YTHDF1 and combine with m6A modified PIK3R1 mRNA, improve the translation level of PIK3R1 mRNA, promote the glycolysis of liver cancer cells through subsequent PI3K/AKT signal transduction pathway and make liver cancer resistant to anti-PD-1 treatment." (PMID 37582735, 2023). "Furthermore, we analyzed the active ingredient-target-pathway network and uncovered that Fumaridine, Lastourvilline, N-feruloyl tyramine, and Cryptopine conclusively contributed to the development of liver cancer by affecting the MTOR, MAPK3, PIK3R1, and EGFR gene." (PMID 35745580, 2022).